IL6 (interleukin 6)
Diseases named in the same sentence as IL6 in open-access papers (continued):
Sharing a sentence is not in itself a finding about the gene and the disease.
endometriosis (continued). "After the rats were euthanized, peritoneal lavage fluid was collected to assess tumour necrosis factor alpha (TNF-α) and interleukin 6 (IL-6), which are the most relevant to the pathogenesis of endometriosis." (PMID 41303437, 2025). "It appears that NF-kB inhibitors and TLR4 agonists lead to the suppression of HMGB1 and decreases in IL-6 levels, demonstrating their involvement in endometriosis and the clinical relevance of this new finding." (PMID 38337827, 2024). "IL-6 is one of the most studied proinflammatory cytokines in endometriosis and is one that is highly expressed in patients with the disease." (PMID 38892003, 2024). "It has been demonstrated that some cytokines, such as tumor necrosis factor-alpha (TNF-a), interleukin-6 (IL-6), and IL-8, are different in endometriosis-affected women compared to controls." (PMID 38555302, 2024). "IL-6 is crucial for macrophage polarization and survival, influencing the broader inflammatory landscape of endometriosis." (PMID 39484721, 2024). "The cytokines IL-1β and IL-6 are known to play important roles in the pathophysiology of endometriosis." (PMID 39141428, 2024). "In the current work, we provide critical mechanistic insights into TET3-mediated regulation of IL-1β and IL-6, 2 key cytokines with well-established roles in endometriosis." (PMID 39141428, 2024). "Several serum cytokines such as interleukins (IL) IL1β, IL-5, IL-6, IL-7 and IL-12 are involved, and their levels were found to be altered in endometriosis as compared to in healthy women." (PMID 39309679, 2024). "Many inflammatory factors, such as tumor necrosis factor (TNF)-alpha, interleukin (IL)-1beta, IL-33 and IL-6, were upregulated in peritoneal fluid of women with endometriosis." (PMID 38961373, 2024). "Following the induction of endometriosis in the mouse model, we treated the animals with IL-6 (5 μg/injection) or PBS in the peritoneal cavity for 15 days." (PMID 39201680, 2024). "Second, IL-6 released from activated macrophages stimulates the migration of endometriotic epithelial cells during formation of extrapelvic endometriosis." (PMID 39141428, 2024). "We demonstrated that inflammation and fibrosis are present at a very early stage of endometriosis and that the inflammatory environment in the peritoneal cavity, which includes interleukin 6 (IL-6), can regulate the expression of miR-21 in vitro and in vivo." (PMID 39201680, 2024). "The peritoneal fluid in women with endometriosis contains abundant proinflammatory cytokines, particularly interleukin 6 (IL-6), which creates a chronic inflammatory state." (PMID 39201680, 2024). "Specifically, the levels of TNFα, IL-1β, and IL-6 are increased in peritoneal macrophages isolated from endometriosis patients." (PMID 39192982, 2024). "SASP gene products identified by RNAseq include many inflammatory biomarkers that have been historically analyzed in endometriosis, including IL-1β, IL-6, IL-8, CCL5, TNF-α, CCL2, MMP3, HMGB1, p16, and p21." (PMID 38879630, 2024). "Regarding female infertility, patients with endometriosis with infertility presented higher concentrations of inflammatory markers IL-6, IL-10, IL-13, and TNF-α than controls." (PMID 38612425, 2024). "TET3 acts as a positive regulator for the expression of proinflammatory genes, such as IL-6 and IL-1β, both of which play well-documented roles in the pathology of endometriosis." (PMID 39141428, 2024). "It has also been observed that it can activate inflammatory leukocytes and stimulate macrophages to produce other cytokines, such as IL-1 and IL-6, which further enhances the proinflammatory environment in women with endometriosis." (PMID 38892003, 2024). "For instance, high concentration of IL-6 is observed in the peritoneal fluid of women with endometriosis." (PMID 38765018, 2024). "Studies have shown that IL-6 levels are significantly elevated in both the serum and peritoneal fluid of women with endometriosis compared to controls." (PMID 39767772, 2024).
endometriosis (continued). "Specifically, the levels of TNFα, IL1β, and IL6 are increased in pelvic MΦ isolated from endometriosis patients." (PMID 38559689, 2024). "The dysregulated cytotoxicity of peritoneal NK cells in endometriosis can be attributed to various cytokines (IL-6, IL-8, IL-1β, IFN-γ, and TNF-α) and inhibitory factors present in both serum and peritoneal fluid." (PMID 39309679, 2024). "The primary outcome was changes in pelvic pain as measured by the Endometriosis Symptoms Severity Scale 29 but were also analyzed Quality of Life outcomes and measurement of the serum concentrations of IL-6 and TNF." (PMID 38697213, 2024). "IL-6 can contribute to the inflammatory milieu characteristic of endometriosis and reflect disease severity." (PMID 39597051, 2024). "Numerous investigations have shown that levels of IL-6 are markedly increased in endometriotic lesions, peritoneal fluid, and serum of women with endometriosis compared to disease-free controls." (PMID 39684860, 2024). "The interplay between TET3 and IL-6 particularly underscores the importance of targeting TET3 in macrophages as a promising strategy to improve outcomes for patients with endometriosis." (PMID 39484721, 2024). "Elevated TNFα, IL-1β, and IL-6 levels have been reported in the blood, peritoneal fluids, and/or eutopic and ectopic endometrial tissues of women with endometriosis." (PMID 39192982, 2024). "IL-6 is elevated in the peritoneal fluid, endometriotic lesions and serum from women with endometriosis." (PMID 39201680, 2024). "Women who have been diagnosed with endometriosis exhibit increased levels of proinflammatory substances, such as tumor necrosis factor-a, interleukin-1b, and interleukin-6." (PMID 38384812, 2024). "Endometriosis induces systemic inflammation through pro-inflammatory cytokines such as IL-1β, IL-6, and TNF-α." (PMID 39381444, 2024). "IL-6 is a pleiotropic cytokine also secreted by macrophages that promotes endometrial cell proliferation and angiogenesis in patients with endometriosis." (PMID 39595086, 2024). "The substantial involvement of inflammatory mediators and diverse cytokines, including TNF-α, IL-1β, and IL-6, in the initiation, proliferation, and progression of epithelial ovarian cancer, akin to the observations made in endometriosis." (PMID 38384812, 2024). "It is associated with increased levels of IL-6, TNF-alpha, and IL-1 beta, representing another pathogenic mechanism associated with the development of endometriosis." (PMID 38337827, 2024). "In the peritoneum of patients with endometriosis, increased concentrations of proinflammatory factors, such as interleukin 6, have been found." (PMID 38276248, 2024). "In a similar study of reference, the expression rate of IL-6 was also higher in patients with endometriosis and it had a dependence on the stage of the disease (higher in III/IV vs. I/II stage)." (PMID 37143676, 2023). "E2 promotes the initial inflammatory mediator, LPS/TLR4, signaling to directly stimulate peritoneal macrophages to secrete TNF-α and IL-6 in the internal milieu of pelvic inflammation within endometriosis." (PMID 37226177, 2023). "Studies from endometriosis mouse models found elevated levels of Tumor Necrosis Factor-alpha (TNFα), interleukin 6 (IL-6), Macrophage Inflammatory Protein 1 alpha (MIP-1α), and MIP-2 in peritoneal macrophages." (PMID 36693853, 2023). "Pro‐inflammatory cytokines, such as interleukin (IL)‐1, IL‐6, and tumor necrosis factor‐alpha, have been detected in patients with endometriosis." (PMID 37693240, 2023). "Specific dietary fatty acids have been proven to influence the circulating levels of inflammatory markers such as Interleukin-6 (IL-6) and others, which are found in higher levels among women with endometriosis." (PMID 36983810, 2023). "The TNF and IL6 data require a more thorough analysis but, in general, support the histological observation of glial activation during endometriosis." (PMID 36879305, 2023).
endometriosis (continued). "IL-6 can activate macrophages and is involved in the cellular proliferation of endometriosis, IL-8 is an angiogenic, pro-inflammatory growth-promoting cytokine involved in inflammatory responses including the activation of many inflammatory cells." (PMID 37893241, 2023). "These microbial imbalances have been correlated with increases in inflammatory markers such as TNF-α and IL-6, both often raised in those with endometriosis." (PMID 38002684, 2023). "The IL-6 levels varied from 4.2 to 2428 pg/mL in the follicular fluids (FF); higher median titers were observed in the endometriosis group than in the control group (152.3 vs. 19.9 pg/mL; p = 0.02)." (PMID 36902616, 2023). "In PF of endometriosis patients compared to controls, three pro-inflammatory cytokines (IL-6, IL-8 and IL-18) were significantly differently expressed." (PMID 36902452, 2023). "Higher levels of expressed IL-6 were measured in the peritoneal fluid and serum from women with endometriosis." (PMID 37143676, 2023). "Inflammation in endometriosis is driven by elevated levels of macrophages and cytokines, including interleukins (IL-1β, IL-6, IL-8, IL-17), tumor necrosis factor α (TNFα), cyclooxygenase 2 (COX-2), and macrophage inhibitory factor (MIF)." (PMID 37834449, 2023). "There are increased levels of pro-inflammatory cytokines, such as TNF-α, IL-1β, IL-6, and IL-17A, in the PF and ectopic lesions of patients with endometriosis, promoting the inflammation and development of endometriosis." (PMID 36865552, 2023). "Decrease in Ruminococcus correlated with an increase in IL-6 in a murine model of endometriosis, resulting in peritoneal inflammation." (PMID 38002684, 2023). "In PF of endometriosis patients, we found Interleukin 18 (IL-18) to be decreased, yet Interleukin 8 (IL-8) and Interleukin 6 (IL-6) to be increased." (PMID 36902452, 2023). "TNF-α, IL-1, and IL-6 participate in the development of endometriosis, and carcinogenesis of the endometrium." (PMID 36834426, 2023). "In the present study, IL-6, IL-8, IL-10, IL-18, IL-23, IFN-α2 and MCP-1, which are associated with endometriosis and considered to be exacerbating factors in endometriosis, were significantly lower in the treated group." (PMID 37629072, 2023). "Endometriosis-associated CCC has been considered a chronic inflammatory disease, as it exhibits high levels of proinflammatory cytokines including IL-1, IL-6, IL-8, IL-10, and TNF-α." (PMID 37627318, 2023). "IL6 represents for some authors a useful marker for endometriosis and AMH is considered as an important indicator of oocyte quality and follicle selection." (PMID 36902616, 2023). "In peritoneal fluid and ectopic endometrium of endometriosis model mice, neutrophil counts and levels of granulocyte colony-stimulating factor (G-CSF) and interleukin-6 (IL-6) were significantly increased." (PMID 36762287, 2023). "In another animal study, however, vitamin D was less effective against endometriosis than omega-3 polyunsaturated fatty acids; when vitamin D was used, only a reduction of IL-6 levels was observed, which was the same as the findings reported earlier." (PMID 37375677, 2023). "IL6 suppresses the cytolytic activity of NK cells in the peritoneal fluid of patients with endometriosis, concomitantly downregulating NK cells’ cytolytic molecules (e.g., granzyme B and perforin)." (PMID 37570749, 2023). "CD8 expression on iNKT cells in combination with the regulatory cytokines IL-6, IL-17 and IL-10 were unaltered between health and endometriosis controls." (PMID 37497226, 2023). "In the peritoneal cavity of endometriosis patients, the immune cells are recruited and secrete excessive levels of proinflammatory cytokines (interleukin (IL)-1, IL-6, TNF, and IFNγ), which promote disease development and progression." (PMID 36358904, 2022).
endometriosis (continued). "Many studies showed that activated macrophages in women with endometriosis are present in significantly higher numbers and secrete cytokines, including IL-6, more intensively." (PMID 35805112, 2022). "IL-6 is a cytokine that plays a role in the pathogenesis of endometriosis and is a biphasic immune molecule that acts as both a pro-inflammatory cytokine and an anti-inflammatory myokine." (PMID 36431970, 2022). "Laboratory studies have shown that peritoneal macrophages in women with endometriosis express cytokines IL-6, IL-1B, and tumor necrosis factor more than in women with benign abnormalities." (PMID 36381357, 2022). "In other preclinical models of endometriosis, it has been reported that the increase in IL-6 and TGF-β1 levels is attributable to the development of endometriosis-like lesions." (PMID 35577867, 2022). "Expression of cytokines IL-2, IL-6, IL-10, and IL-15 was lower in endometriosis lesions than in eutopic endometrium in the secretory phase." (PMID 35269619, 2022). "Increased miR-142-3p seems to reduce steroid sulfatase and IL-6 activity, suggesting a dual effect on steroidogenic and inflammatory pathways in endometriosis." (PMID 35054341, 2022). "Analysis of peritoneal fluid in women with endometriosis showed increased levels of pro-inflammatory and pro-angiogenic cytokines IL-6 and IL-8, which is consistent with previous observations." (PMID 35408850, 2022). "It is also worth noting that elevated IL-6 levels inhibit NK cell activity in the peritoneal fluid of patients with endometriosis." (PMID 35805112, 2022). "IL-1β, IL-6, and IL-15 expressions were lower, and IL-4 was higher in endometriosis lesions compared to that in eutopic endometrium in the proliferative phase." (PMID 35269619, 2022). "There is a need for future studies aimed at finding miRNAs that regulate the expression of EP- and endometriosis-associated genes, such as VEGF, ESR1, IL-6, and IL-8." (PMID 35408850, 2022). "Several cytokines are elevated in the peritoneal fluid and in the serum of patients with endometriosis; however, the cytokines IL-1β, TNF-α, IL-6, and IL-10 play a fundamental role in the pathogenesis of endometriosis." (PMID 35807280, 2022). "IL-6 contributes to the implantation of endometrial cells, and its levels in the peritoneal fluid of women suffering from endometriosis are significantly increased." (PMID 36431970, 2022). "In endometriosis-like lesions, levels of interleukin 6 (IL-6) and prostaglandin E2 (PGE2) increased, whereas that of SERPINA1 (known as alpha-1 antitrypsin) decreased." (PMID 36093086, 2022). "Women with endometriosis and unexplained infertility have been observed by other investigators to have higher endometrial IL-6 concentrations." (PMID 36568084, 2022). "There is also an increase in the proinflammatory and anti-inflammatory cytokines IL-1, IL-4, IL-6, IL-8, IL-10 and TNFα in the serum and in peritoneal fluid of women with endometriosis, particularly in advanced stages." (PMID 35888644, 2022). "The proinflammatory interleukin, IL-6, has been identified in high concentrations in endometriosis; however, some of the contradicting studies exist." (PMID 33435569, 2021). "Between stages III and IV of endometriosis, significant differences in concentrations of IL-6 (p = 0.040), hs-CRP (p = 0.007) and CA 125 (p < 0.001) were observed." (PMID 33669013, 2021). "The authors documented significantly higher serum IL-6 concentrations in women with endometriosis in comparison to the control group of healthy women." (PMID 33669013, 2021). "The results demonstrated significant alterations in the FF concentration of IL-6 and IL-3 in endometriosis women compared to the controls." (PMID 35571503, 2021). "In this regard, it is worth noting that in endometriosis, the level of IL6 in the peritoneal fluid is usually elevated compared to healthy women and shows a positive correlation with the size and quantity of the endometrioid lesions." (PMID 34680403, 2021).
endometriosis (continued). "In this review, four studies showed that IL-6 is overexpressed in endometriosis and the level of its expression depends on the disease’s severity." (PMID 33435569, 2021). "Table III shows the AUC, sensitivity, and specificity of IL-3, IL-5, and IL-6 for diagnosis of endometriosis with confidence intervals." (PMID 35571503, 2021). "Consistent with our data, IL-6 has been shown to discriminate between patients with endometriosis and controls." (PMID 34829910, 2021). "On the other hand, tissue damage induced by the growth of endometriosis activates macrophages to produce IL-6, and as a result, inflammation occurs." (PMID 35571503, 2021). "The present study also indicated that IL-6 concentration significantly increases in women with endometriosis." (PMID 35571503, 2021). "The administration of the vaccine before the induction of endometriosis prevented the increase of Th-2 dependent cytokines: IL4, IL6, and IL-10, which is typically observed during the development of endometriosis." (PMID 34945174, 2021). "Higher levels of expressed IL-6 were also measured in the peritoneal fluid and serum from women with endometriosis, along with TGF-β isoforms, IL-1β, IL-10, and IL-17AF." (PMID 33435569, 2021). "The sensitivity and specificity of the serum IL-6 to predict the presence of endometriosis were 90% and 93.7%, respectively." (PMID 35571503, 2021). "Previous reports have shown that several inflammatory cytokines, such as IL-6, interleukin-8 (IL-8), and tumor necrosis factor-α (TNFα), were significantly elevated in the peritoneal fluid of patients with endometriosis." (PMID 34872568, 2021). "So far, only one study investigated the effect of resveratrol treatment on plasma and PF levels of IL‐6 on an experimental rat model of endometriosis." (PMID 33325132, 2021). "An increased number of macrophages has been reported in the PF of the women with endometriosis, which produces more IL-6, demonstrating the involvement of IL-6 in the pathogenesis of the disease." (PMID 35571503, 2021). "In rat models with surgically-induced endometriosis, V. opulus significantly decreased the volume of endometriotic lesions, and lowered the serum levels of IL-6, VEGF and TNF-α." (PMID 33804660, 2021). "FBs in endometriosis cells produced higher levels of inflammatory factors IL-6 in ectopic endometrium than in eutopic endometrium from endometriosis women, while the corresponding receptors were expressed in macrophages/monocytes and mast cells." (PMID 34233737, 2021). "IL‐6 is one of the most prominent pro‐inflammatory cytokines and angiogenic factors in endometriosis." (PMID 33325132, 2021). "GNRH1, PGR, TNF, CYP19A1, and IL6 were mentioned with the highest frequencies in endometriosis-related articles." (PMID 34917684, 2021). "It was found that in women with endometriosis, even eutopic endometrial cells produce higher quantities of IL-6 under basal conditions when compared to women with endometriosis." (PMID 34073257, 2021). "The mean concentration of IL-6 showed a significant increase in the endometriosis women (47.5 ± 72.8 pg/ml) compared to the control group (9.7 ± 6.5 pg/ml, p = 0.03)." (PMID 35571503, 2021). "Nevertheless, hypoxia was demonstrated to be the upstream factor, which upregulates VEGF-A, IL-6, and IL-8 in endometriosis." (PMID 34945174, 2021). "IL-6 as a pro-inflammatory cytokine contributes to the initiation and development of endometriosis via the cytokine network." (PMID 35571503, 2021). "We showed that S1P is produced via SphK in endometriotic lesions and is involved in the pathogenesis of endometriosis, inducing proliferation of endometriotic cells and induction of IL-6, an inflammatory agent." (PMID 34829748, 2021). "The results suggested that the bioactive compounds of WJD against endometriosis included 48 targeted genes, among which IL6 and ESR1 were closely related to inflammation and the endocrine system, respectively." (PMID 34257679, 2021).